CD86 (CD86 molecule)
Diseases named in the same sentence as CD86 in open-access papers (continued):
Sharing a sentence is not in itself a finding about the gene and the disease.
neuropathic pain (1 paper, 2025). Chronic pain caused by damage to nerve fibers. "The high affinity and specificity enable it to target CD86‐positive M1 microglia in neuropathic pain mice, demonstrating its in vivo targeting capability." (PMID 40585759, 2025).
Nocardia infection (1 paper, 2022). "Therefore, we detected the expression of markers of M1 (iNOS, CXCL-10, and CD86) and M2 (CD206 and ARG1) microglia after Nocardia infection using BV2 cells." (PMID 36352407, 2022).
oral cancer (1 paper, 2023). "Interestingly, loss of RGS12 inhibits the expression of M1 macrophage (CD86) but promotes the expression of M2 macrophage (CD163) in 8-week 4NQO-induced oral cancer tissues." (PMID 36797232, 2023).
osteonecrosis (1 paper, 2024). A none disease characterized by death of bone tissue due to a lack of blood supply. "Among these, horizontal pleiotropy was detected in MR-Egger regression with regard to two features related to drug-induced osteonecrosis (CD62L − HLA DR + + monocyte %monocyte and CD62L − CD86 + myeloid DC %DC)." (PMID 38654114, 2024).
otitis media (1 paper, 2021). Inflammation of the anatomical structures of the middle ear, which is most often caused by an infectious process. "The phenotypes of B cells in the ear, nose, and throat, especially in patients with otitis media, were shown to be CD5low, CD23high, CD43low, B220high, sIgMlow, sIgDhigh, Mac-1low, CD80(B7.1)low, CD86(B7.2)low, and Syndecam-1low." (PMID 33801155, 2021).
pemphigus (1 paper, 2021). Pemphigus is a group of rare autoimmune diseases that cause blistering of the skin and mucous membranes (mouth, nose, throat, eyes, and genitals).This conditioncan occur at any age, but often strikes people in middle or older age. "Direct comparison of our dataset to previously published human pemphigus datasets revealed five conserved differentially expressed genes: CD19, WIF1, CXCL10, CD86, and S100A12." (PMID 34660634, 2021).
peripheral nerve injury (1 paper, 2020). Injury to a peripheral nerve. "We also calculated an M2 to M1 ratio: [CD206+]/[CD206−, CD86+], a metric shown to be predictive of neural regeneration in a peripheral nerve injury model and correlated indirectly to improved outcomes in a TBI model." (PMID 32563258, 2020).
peritonitis (1 paper, 2018). Inflammation of the peritoneum (tissue that lines the abdominal wall and covers most of the organs in the abdomen). "During thioglycolate-induced peritonitis, adoptively transferred macrophages with Egr2 knockdown failed to become activated as determined by upregulation of MHC class II and CD86." (PMID 30443252, 2018). "On day 4 of thioglycollate-induced peritonitis, adoptively transferred DsRed+F4/80+ macrophages transfected with control siRNA upregulated MHC class II and CD86, while macrophages with siRNA for Egr2 had a significantly lower level of expression of these molecules." (PMID 30443252, 2018).
pertussis (1 paper, 2016). A contagious bacterial respiratory infection caused by Bordetella pertussis. "OMVs were benchmarked against licensed vaccines, including Bexsero and whole cell pertussis formulations, with respect to Th-polarizing cytokine and prostaglandin E2 production, as well as cell surface activation markers (HLA-DR, CD86, and CCR7)." (PMID 28008331, 2016).
pleural cancer (1 paper, 2024). A primary or metastatic malignant neoplasm affecting the pleura. "Correspondingly, flow cytometry analysis and immunohistochemistry staining of pleural cancer nodules both demonstrated an increase in the CD86+ subset and a decrease in CD206+ subset." (PMID 38589867, 2024).
Pleural effusion (1 paper, 2021). The presence of an excessive amount of fluid in the pleural cavity. "This study shows that CD16+ monocytes isolated from pleural effusion of TPE patients exhibit a more mature phenotype than CD16- monocytes, such as costimulatory molecules CD40, CD80, CD86 and HLA-DR." (PMID 34237073, 2021).
podoconiosis (1 paper, 2024). A disease of the lymphatic vessels of the lower extremities that is caused by chronic exposure to irritant soils. "The three DC subsets had significantly higher levels of CD40 expression while expression of CD86 was higher only in myeloid DCs in podoconiosis patients compared to the healthy controls." (PMID 38448477, 2024). "Expression of the activation markers CD40 and CD86 was significantly higher on classical monocytes from podoconiosis patients compared to healthy controls, with median values of 35.6% vs 25.5% for CD40 and 13.7% vs 7.4% for CD86 (P = 0.03, P = 0.001, respectively)." (PMID 38448477, 2024). "The expression of HLA-DR, CD40, CD86, and CD36 was analyzed on monocytes from 43 podoconiosis patients and 34 healthy controls." (PMID 38448477, 2024). "However, the expression of the co-stimulatory molecules CD86 and CD40 among classical monocytes was higher in podoconiosis patients." (PMID 38448477, 2024).
polymyositis (1 paper, 2024). A rare idiopathic inflammatory myopathy characterized by symmetric proximal muscle weakness and elevated muscle enzymes. "Several immune cell phenotypes exhibited the ability to increase the risk of polymyositis, such as PB/PC %B cells, CD86+ myeloid DCs, and CD28 on Treg cells." (PMID 39470507, 2024).
prion disease (1 paper, 2016). A transmissible disease that is caused by a protein that is able to induce abnormal folding of normal cellular proteins, leading to characteristic spongiform brain changes, which are associated with neuronal loss without an inflammatory response. "In order to evaluate the activation state of microglia at onset and end-stage prion disease in wild-type and Neil3 Ko mice we compared expression levels of microglial markers Cd68, Cd86 and inflammation markers TNFα and Il1ß at both time-points." (PMID 27886261, 2016).
psoriasis vulgaris (1 paper, 2016). Plaque psoriasis is the most common presentation of psoriasis. "The proportion of CD19+CD86+ B cells in PBMCs was only increased inpatients with psoriasis vulgaris at the active stage compared to HCs(P<0.01)." (PMID 27532281, 2016). "However, the ratio ofCD19+CD86+ B cells was only upregulated in PBMCs in psoriasis vulgaris at the activestage." (PMID 27532281, 2016).
Renal insufficiency (1 paper, 2025). A reduction in the level of performance of the kidneys in areas of function comprising the concentration of urine, removal of wastes, the maintenance of electrolyte balance, homeostasis of blood pressure, and calcium metabolism. "Finally, for Renal insufficiency, 3,041 genes and 363 related proteins were identified, with 72 gene-protein overlapping targets such as ADAM15, CD86, and AARSD1." (PMID 41340073, 2025).
rosacea (1 paper, 2022). A chronic erythematous skin disorder that affects the face. "And hematoxylin and eosin staining and immunohistochemical staining of skin samples of rosacea showed higher expression of CD86 and profound infiltration of macrophages in previous study." (PMID 36091020, 2022).
SARS-CoV infection (1 paper, 2021). "Furthermore, reductions of CD86 and MHC-II in CD169+ M2 macrophages were observed to a lesser extent upon SARS-CoV infection." (PMID 34122407, 2021).
scrub typhus (1 paper, 2021). Scrub typhus is a rare dust mite-borne infectious disease caused by the Orientia tsutsugamushi bacterium and characterized clinically by an eruptive fever which is potentially serious. "The percentages of both CD86+ and CD274+ pDCs were significantly higher in scrub typhus patients compared to the HCs (for CD86+ pDCs, median 39.9% versus 11.3%, P = 0.031; and for CD274+ pDCs, 13.6% versus 0.2%, P = 0.001)." (PMID 34276693, 2021). "After reproducing the pro-inflammatory milieu using a cytokine cocktail including IFN-γ, IL-12, and TNF-α, we observed the dynamics of CD86 and CD274 expression patterns in pDCs and cDCs, which was similar to our data in scrub typhus patients." (PMID 34276693, 2021).
Shock (1 paper, 2019). The state in which profound and widespread reduction of effective tissue perfusion leads first to reversible, and then if prolonged, to irreversible cellular injury. "To investigate whether the effect exhibited by LA1 on endotoxic shock was due to inhibition of LPS-induced pro-inflammatory response in macrophages, we first examined the expressions of CD86 and CD40 in macrophages obtained from either LA1 or vehicle-treated mice after LPS treatment." (PMID 30809230, 2019).
silicosis (1 paper, 2018). Silicosis is a respiratory disease caused by breathing in (inhaling) silica dust. "In summary, our study demonstrated that DCs accumulated in lung tissues of silica dust exposure rats and regulated the polarization of Th1/Th2 cells via CD80, CD86, MHC-II and IL-12 expressions, indicating that DCs may play a critical role in modulating immune homeostasis during silicosis in rats." (PMID 35541981, 2018).
Sjögren’s syndrome (1 paper, 2024). "Interestingly, splenic MDSCs of mice in early stage of experimental Sjögren’s syndrome (10 days postimmunization) showed an immature phenotype (low expression levels of CD40, CD80, CD86 and MHC-II markers) and potent suppressive activity of T cell proliferation." (PMID 38495880, 2024).
splenic marginal zone lymphoma (1 paper, 2025). Splenic marginal zone lymphoma is a rare, indolent B-cell non-Hodgkin lymphoma characterized by abnormal clonal proliferation of mature B-lymphocytes with involvement in the spleen, bone marrow and, frequently, the blood. "In splenic marginal zone lymphoma (SMZL) the level of CD86 increased following the stimulation of their toll‐like receptors." (PMID 40635602, 2025).
squamous cell carcinoma (1 paper, 2025). A carcinoma arising from squamous epithelial cells. "We observed higher expression of immune checkpoint ligands (PVR, NECTIN2, CD274, CD80, and CD86) in the tumor cells at the invasive front of the squamous cell carcinomas." (PMID 41309580, 2025).
ST Elevation Myocardial Infarction (1 paper, 2022). A myocardial infarction that produces elevation in the ST segments of the ECG. "They found a downregulation of immature (CD1a+) DCs in ST-elevation myocardial infarction (STEMI), non-STEMI, and coronary artery disease (CAD) patients and an upregulation of mature (CD86+) DCs in CAD patients." (PMID 35615580, 2022).
steatosis (1 paper, 2025). Increased lipid within the cytoplasm of cells. "Proinflammatory M1 macrophages (F4/80+CD11C−CD206− or CD86+) were significantly increased in diabetic vs. non-diabetic mice/rats (p < 0.05), and associated with liver abnormalities like steatosis, inflammation, necrosis, and fibrosis." (PMID 40362271, 2025).
stomach adenocarcinoma (1 paper, 2019). "Besides PD-L1, PD-L2, PD-1, CD80, CD86, CTLA-4, Tim-3, LAG3, and 4-1BB, we found the increase of an inducible co-stimulator (ICOS) expression in both HPV-positive head and neck squamous cell carcinoma and EBV-positive stomach adenocarcinoma tumors." (PMID 30911684, 2019).
subarachnoid hemorrhage (1 paper, 2024). A serious neurological disorder characterized by intracranial hemorrhage into the subarachnoid space. "In turn, the knockdown of endogenous TSG-6 by siRNA elevated the (CD86+) M1 vs. (CD163+) M2 ratio in cerebral microglia and aggravated neurological deficits 24 h after subarachnoid hemorrhage." (PMID 39329947, 2024).
synovial sarcoma (1 paper, 2021). "Taken together, sunitinib treatment of both bone and synovial sarcoma cells induced a significant upregulation of CD80, CD86, CD83 and CCR7 which are essential for full DC maturation." (PMID 33717062, 2021).
synovitis (1 paper, 2020). Inflammation of a synovial membrane. "To identify the distribution of different macrophage subsets in OA ST with moderate-grade synovitis, we evaluated the expression of CD86 and CD206 in 6 out of 8 different cases." (PMID 33321965, 2020).
tendinopathies (1 paper, 2024). "Interestingly, both tendinopathies showed similar CD86 (M1 macrophage) and CD206 (M2 macrophage) expression levels for healthy, sham, and pathological groups in tendon proper and paratenon areas." (PMID 38790957, 2024). "However, even though not statistically significant, both tendinopathies showed a lower CD86/CD206 ratio in the pathological group at the paratenon compared to the tendon proper." (PMID 38790957, 2024).
thymic lymphomas (1 paper, 2015). "Furthermore, by gating of the CD11c+ DCs cell population using flow cytometry analysis, we confirmed that the Ia, CD86, CD80, CCR7, CD40 and IL-12 proteins of CD11+ DCs were all down-regulated in thymic lymphomas." (PMID 25923834, 2015).
ulcers (1 paper, 2024). "In the same context, the current study found that the M1 macrophage markers CD38 and CD86 increased as a response to ethanol-induced ulcers." (PMID 39314751, 2024).
upper respiratory tract infection (1 paper, 2024). "Similar results were observed in clinical trials, reporting that the oral administration of LC-Plasma for 14 days could increase CD86 and HLA-DR expression, thus reducing the number of incidences (days) of upper respiratory tract infection in male athletes undergoing high-intensity exercise." (PMID 39597693, 2024).
uremia (1 paper, 2010). A clinical syndrome associated with the retention of renal waste products or uremic toxins in the blood. "Firstly, uremia causes a reduction of the essential costimulatory molecule B7-2 (CD86) on antigen-presenting cells which decreases the activation of helper T-lymphocyte cells." (PMID 20886005, 2010).
Ureteral obstruction (1 paper, 2019). Obstruction of the flow of urine through the ureter. "Representative images showed that the expressions of CD11c and F4/80 were highlighted in the left kidney with ureteral obstruction at 14 days after operation, but the expression of CD86 was observed in both the obstructed left kidney and the unobstructed right kidney." (PMID 30949209, 2019).
uveitis (1 paper, 2023). An inflammatory process affecting a part of or the entire uvea. "It is suggested that, in patients treated with ICIs, inhibition of the PD-L1/PD-1 and CD86/CTLA4 pathways induces ocular inflammation, causing uveitis." (PMID 37604934, 2023).
vitamin D deficiency (1 paper, 2013). A nutritional condition produced by a deficiency of VITAMIN D in the diet, insufficient production of vitamin D in the skin, inadequate absorption of vitamin D from the diet, or abnormal conversion of vitamin D to its bioactive metabolites. "TLR4 and CD86 expression were not affected by vitamin D deficiency in our study." (PMID 23875738, 2013).
vitiligo (1 paper, 2025). Generalized well circumscribed patches of leukoderma that are generally distributed over symmetric body locations and is due to autoimmune destruction of melanocytes. "The expression of co-stimulatory molecules on DCs, including CD80 and CD86, is notably increased in vitiligo patients, enhancing their antigen-presenting ability and promoting the activation and proliferation of T cells, particularly CD8+ T cells, which contribute to the destruction of melanocytes." (PMID 41169396, 2025). "In vitiligo, DAMPs enhance the maturation of DCs, elevating the expression levels of co-stimulatory molecules such as CD80 and CD86, thereby augmenting their antigen-presenting capabilities." (PMID 41169396, 2025). "In vitiligo, activated DCs migrate to regional lymph nodes, where they upregulate co-stimulatory molecules like CD80 and CD86, present melanocyte antigens to T cells, and provide the second signal for full activation." (PMID 41169396, 2025).
tumor (1,404 papers, 1998 to 2026). "Although TNF-α production by intratumoral dendritic cells showed no major differences, rBCG-treated mice exhibited significantly elevated CD86 expression in tumor-associated macrophages, suggesting improved costimulatory capacity within the tumor niche." (PMID 41522339, 2026). "Our study also found that treatment with CV1 in combination with CDH17-CAR-NK92 led to an increase in CD69+ and CD86+ macrophages, potently implicating the enhanced antitumor activity of tumor-associated macrophages." (PMID 40487639, 2025). "In tumor, high proportions of CD86- and NKp46-expressing tumor-infiltrating iNKT cells were associated with better outcomes." (PMID 41562072, 2025). "FcγRI‐CAR‐HMs treatment shifted tumor‐associated macrophages (TAMs) from an immunosuppressive to immunostimulatory phenotype, evidenced by upregulated CD86/IL‐1β/IL‐12/TNF‐α and downregulated CD206/TGF‐β." (PMID 40847445, 2025). "Of note, a heatmap based on GSEA showed several tumor-associated immune checkpoints, such as H2-Ab1, CD86, CD80, and CD276, CD274 (Pdl1), were downregulated upon Prmt3 deletion." (PMID 40050608, 2025). "In ST2-deficient mice, tumor-infiltrating CD11b+CD11c- macrophages, exhibit decreased expression of the co-stimulatory receptor CD86 and produce increased levels of the immunosuppressive enzyme Arg1." (PMID 39931535, 2025). "High CD163 expression in the tumor stroma of the primary was associated with RFS, while high CD86 expression in the tumor nest of brain metastases correlated with longer brain metastasis-specific survival." (PMID 40510346, 2025). "Flow cytometry analysis of tumor‐associated macrophages (TAMs) further revealed a substantial increase in M1 macrophages (CD86+F4/80+) in the Cu2O@EG + MW compared to PBS, Cu2O@EG alone, and MW alone." (PMID 40789052, 2025). "This work also demonstrates that anti-CD86 blocks the Treg expansion in the tumor caused by radiation therapy, consistent with our data." (PMID 41417245, 2025). "The activation of tumor-associated macrophages was evaluated, in which the M1-phenotype polarized macrophage (F4/80+CD86+CD206−) percentage increased from 20.40% in the control group to 84.00% in the NZCB + US group." (PMID 40739587, 2025). "This correlated with prolonged intratumoral IFNγ release and CD86 upregulation on tumor-associated myeloid cells." (PMID 39889712, 2025). "DCs capture tumor-associated antigens and express co-stimulatory molecules, such as CD86 and CD80, forming peptide-MHC complexes that are presented to T lymphocytes to elicit an anti-tumor immune response." (PMID 40303336, 2025). "In a similar fashion to ovarian cancer, the expression of costimulatory molecules CD80 and CD86 as well as IL12 is upregulated by tumor‐associated DCs and macrophages." (PMID 38109851, 2024). "Nivolumab and ipilimumab, two ICIs that target CTLA-4 and PD-1, induce T cell activation and cause tumor cells death by binding to B7 ligands CD80 and CD86 expressed on antigen-presenting cells (APCs) and PD-L1 on either tumor cells or APCs, respectively." (PMID 38443363, 2024). "After NK-LNP(PA/pDNA) treatment, M1 macrophage polarization markers associated with antitumor immunity (iNOS and CD86) were increased, while M2 macrophage markers associated with tumor progression (CD163 and CD206) were decreased compared to M0 macrophages." (PMID 39339179, 2024). "To further assess MDM/TAM profiles, we evaluated expression of positive co-stimulatory molecule CD86, that is associated with proinflammatory immune responses and enhancement of anti-tumor T cell function." (PMID 39414902, 2024). "In contrast, blockade of TLR5 attenuated C5aR1 inhibition-regulated tumor suppression in association with a decrease in CD86 expression and glycolysis in macrophages." (PMID 38331868, 2024).